CD74 (CD74 molecule)
Diseases named in the same sentence as CD74 in open-access papers (continued):
Sharing a sentence is not in itself a finding about the gene and the disease.
thymic atrophy (1 paper, 2026). "Undesirably, although OVX ameliorated age-related thymic atrophy, it appeared to simultaneously increase autoimmune susceptibility by downregulating thymic Cd74 expression." (PMID 41596668, 2026). "Fifthly, we observed that although OVX ameliorated thymic atrophy during aging, it seemed to simultaneously enhance autoimmune susceptibility in females by downregulating Cd74." (PMID 41596668, 2026).
tongue squamous cell carcinoma (1 paper, 2025). A squamous cell carcinoma that arises from the tongue. "Additionally, flow cytometric analysis of murine tongue squamous cell carcinoma showed that the positive CD74+PDGFRB+ apCAFs was 1.37% in the murine tongue squamous cell carcinoma while we could not find any positive CD74+PDGFRB+ apCAFs in the normal control tissue." (PMID 39891284, 2025).
uveitis (1 paper, 2025). An inflammatory process affecting a part of or the entire uvea. "In unadjusted logistic regression models, elevated anti-CD74 Abs were associated with older age, male sex, radiographic disease status, uveitis, increased BMI (body mass index), BASMI, and current treatment with bDMARDs." (PMID 40063233, 2025). "We also found an association between the presence of anti-CD74 antibodies and uveitis, an extra-musculoskeletal manifestation of axSpA known to be more prevalent in the radiographic disease state as well as in HLA-B27 positive individuals." (PMID 40063233, 2025). "Although patients with elevated anti-CD74 Abs seem to have a higher disease severity, with systemic inflammation (CRP) and extra-musculoskeletal manifestations (uveitis), the quality of health as noted by the EuroQol 5-domain questionnaire was not reduced in patients with elevated anti-CD74 Abs." (PMID 40063233, 2025).
vitiligo (1 paper, 2022). Generalized well circumscribed patches of leukoderma that are generally distributed over symmetric body locations and is due to autoimmune destruction of melanocytes. "Inflammatory and immune response–related genes such as CD74, IFI27, IFI6, and IFITM1 were also significantly increased, and this was further confirmed by the hallmark pathway enrichment analysis of the genes highly expressed in vitiligo lesional skin using the Molecular Signatures Database (MSigDB)." (PMID 35653192, 2022).
tumor (446 papers, 2005 to 2026). "In some cancer types, elevated CD74 expression was associated with signatures of M1 macrophage infiltration, reduced DNA repair gene expression, and enhanced immunogenicity in multiple tumor types." (PMID 41597203, 2026). "Compounds such as ISO-1 inhibit CD74-dependent cancer cell survival signaling and render tumor cells more susceptible to chemotherapy or immunotherapy." (PMID 41597203, 2026). "Among the various fusion proteins associated with cancer, those involving CD74 have attracted considerable attention because of their involvement in tumor formation and potential therapeutic implications." (PMID 41439980, 2025). "Previous studies have implicated CD74-MIF signaling in promoting tumor progression by suppressing cytotoxic immune responses and enhancing macrophage-mediated immune evasion." (PMID 40364843, 2025). "Our method can not only uncover disease-causing genes with abnormal expression in tumor samples such as CD74, HGF, but it can also identify genes with stable expression yet crucial roles in LUSC, such as BRAF, KDM6A, MAP2K1, and TPR." (PMID 40136480, 2025). "These cells stimulated immunosuppression and tumor-associated macrophage (TAM) differentiation by interacting with macrophages via MIF-(CD74+CD44) signaling." (PMID 40936936, 2025). "It has been shown that low CD74/high M2 signature is linked to increased tumor aggressiveness, while CD74 expression, associated with M1 macrophages, correlates with longer patient survival." (PMID 41450919, 2025). "Potential mechanisms identified in our studies include increased App–Cd74 interactions from neutrophils to macrophages in primary infection, which has been shown to reduce phagocytic ability in tumor-associated macrophages." (PMID 40736456, 2025). "In our study, we observed high expression of antitumor-associated antigen processing and presentation genes in the tumor microenvironment of NSCLC patients with high CD74 expression." (PMID 40470045, 2025). "Dysregulated CD74 expression or turnover is linked to pathological immune activation, tumor progression, and resistance to therapy." (PMID 41439980, 2025). "This synergistic effect also induces macrophage reprogramming from M2 protumor Spp1+ tumor-associated macrophages (TAMs) to Cd74+ TAMs, which act as antigen-presenting cells (APCs)." (PMID 40312419, 2025). "Co-expression of MIF and its putative receptor CD74 in NSCLC is associated with greater tumor vascularity and greater levels of angiogenic CXC chemokines." (PMID 38685050, 2024). "High expression of the zinc finger protein ZEB1 promotes the differentiation of tumor-associated macrophages into cancer-promoting macrophages (M2) by upregulating CD74 expression in tumor cells, thus inducing immune escape and leading to poor prognosis." (PMID 39118044, 2024). "Using the CellChat R package, intercellular communication analysis revealed that tumor-associated macrophages (TAMs) interact with other cells in the PCa TME primarily through MIF - (CD74+CXCR4) and MIF - (CD74+CD44) ligand-receptor pairs." (PMID 38663915, 2024). "One example is the migratory inhibition factor (MIF), which correlates with poor prognosis, and its receptor, CD74, found expressed on tumour-associated macrophages, DCs and MDSC." (PMID 38893071, 2024). "Elevated serum MIF levels in NSCLC predict worse overall and progression-free survival, and co-expression with CD74 correlates strongly with enrichment of tumor-associated CXC chemokines and tumor vascularization." (PMID 38732068, 2024). "High CD74 expression is associated with the abundance of a variety of immune cell types, mediating interactions among tumor and immune cells and shaping the malignant behavior of HCC." (PMID 39118044, 2024).
tumor (continued). "Having confirmed that CD74 gene expression was associated with favorable OS, we next investigated the underlying correlation between CD74 gene expression status and the tumor microenvironment." (PMID 38280003, 2024). "Our work illustrated that the gene and protein expressions of CD74 were associated with clinical outcomes, immune subtypes in tumor microenvironment, and immune responses to ICIs treatment." (PMID 38280003, 2024). "Collectively, these results demonstrate that CD74+ tumour cells are associated with worse prognosis in LSCC." (PMID 39113235, 2024). "In contrast to the limited effect of CD74 deficiency in B cells on the tumor load, deficiency of CD74 in DCs remarkably reduced tumor growth." (PMID 39576827, 2024). "Elevated CD74 expression was associated with reduced levels of mismatch-repair genes and homologous repair gene signatures in over 10 tumor types." (PMID 38582956, 2024). "Another issue raised by our data concerns the biological effect of concomitant TIMP‐1 and CD74 expression and their association in tumor cells." (PMID 37081824, 2023). "In summary, our study indicates that CD74 is a biomarker associated with tumor progression and inflammation in PDAC." (PMID 37629174, 2023). "The peptide C36L1, a 17-mer peptide that binds to CD74 on tumor-associated macrophages and DCs, was shown to block MIF’s immunosuppressive activities in melanoma models in vitro as well as in vivo." (PMID 36672343, 2023). "Three tumor-associated antigens, CD74, IRF1, and PSME2, that showed overexpression, amplification, and mutation and were linked with prognosis and immune cell infiltration, were identified." (PMID 36226063, 2022). "Patients with higher levels of tumor-associated CD74 had significantly better outcomes in comparison with those with lower levels and high levels of IRF1 and PSME2 were also linked with better prognosis." (PMID 36226063, 2022). "CD74 has been implicated to play a tumor-progression role in the immune microenvironment of CM patients." (PMID 36466837, 2022). "CD74 is a cell surface receptor for macrophage migration inhibitory factor and is associated with tumour progression and metastasis." (PMID 34957096, 2021). "MIF/CD74 is a well-established pro-tumorigenic signalling in several solid malignancies partially by participating in the alternate activation of tumour‐associated macrophages." (PMID 34187256, 2021). "High expression of CD74 in brain metastatic tumour cells can cause the processing of functional HLA class II cells, and is associated with a better prognosis." (PMID 34957096, 2021). "Our immunohistochemical data are in line with those of previous studies that demonstrated MIF and CD74 expression by tumor-associated fibroblasts, leukocytes and endothelial cells." (PMID 31866994, 2019). "We observed that CD74 expression on tumor cells is a strong positive prognostic marker in brain metastasis patients and positively associated with tumor-infiltrating T-lymphocytes (TILs)." (PMID 29490700, 2018). "CD74 was associated with patient age (p = 0.001), tumor grade (p = 0.003), and ER status (p = 0.006)." (PMID 27058619, 2017). "Deregulation of Cd74 expression is associated with disturbed tumor immune surveillance, which in part is believed to be a result of impaired endogenous tumor antigen presentation." (PMID 20416035, 2010). "Moreover, CD74 expression in cancer cells and tumor-associated immune cells is increasingly recognized as a double-edged sword." (PMID 41597203, 2026). "In many malignancies, CD74 expression is linked to tumor progression and poor clinical outcome." (PMID 41597203, 2026). "MIF secreted by stromal cells could bind CD74 on tumor epithelial cells, and MIF-deficient stromal cells are known to exhibit reduced functionality." (PMID 40835826, 2025).
tumor (continued). "Expression of MHC-II genes including HLA genes, CIITA, and CD74 were associated with an anti-tumor T cell response, represented by positive correlation with proportion of infiltrating CD8 + T cells, and negative correlation with infiltration of immunosuppressive T regs." (PMID 40361136, 2025). "We further identified that high-RiboSis-activity subpopulations drive microenvironmental immunosuppression via the MIF-(CD74+CD44) axis: CellChat analysis validated this axis promotes myeloid cell polarization toward M2-type tumor-associated macrophages while impairing T-cell activation." (PMID 41394823, 2025). "CD74 is a type II cell surface receptor found to be highly expressed in several hematological and solid cancers, due to its ability to activate pathways associated with tumor cell survival and proliferation." (PMID 37958963, 2023). "Higher mRNA levels of ACAP2, ECHDC3, EGR1, and CD74 were highly associated with tumor development." (PMID 35999505, 2022). "Furthermore, co-expression of MIF and its receptor CD74 in NSCLC is associated with greater tumor angiogenesis and angiogenic CXC chemokine levels." (PMID 35842634, 2022). "In addition, we found that the CD74 pathway plays an important role in tumor associated microphages (TAM) enriched TME formation for UCOGCP, providing potential therapeutic targets for the treatment of UCOGCP." (PMID 35733218, 2022). "Since the expression of Vegfa is downregulated in Mif-deficient tumors, we examined whether tumor cells themselves are able to express angiogenic genes via MIF binding to CD74 to activate MAP kinases to induce VEGF and IL8 expression." (PMID 33542244, 2021). "CD74 has been associated with tumor progression and metastasis." (PMID 31692299, 2020). "CD74 is expressed by tumor cells in BM and is associated with a better overall survival in vivo." (PMID 29490700, 2018). "Indeed, several studies have shown that the level of CD74 expression is proportionality associated with tumor grade." (PMID 29190904, 2017). "One interpretation of our observation is that the functional implication of CD74/MHCII expression in terms of activation of immune responses is common to all subtypes but that tumor susceptibility to the immune system is peculiar to Basal-like tumor cells." (PMID 27058619, 2017). "Moreover, tumor invasion in pancreatic cancer and thyroid carcinoma were reported to be associated with CD74." (PMID 27626171, 2016). "In addition, the pattern of the App-Cd74 signaling suggested incremental communications between epithelial cells and immune cells during the occurrence of precancerous lesions, and it was reported to be implicated in tumor progression and metastasis." (PMID 40658605, 2025). "Additionally, high CD74 protein expression (≥ 10% of the tumor area occupied by CD74 stained immune cells) at baseline was associated with better progressive-free survival (HR = 0.21, 95% CI 0.06–0.68, p = 0.0065) and OS (HR = 0.35, 95% CI 0.12–1.08, p = 0.0615)." (PMID 38280003, 2024). "Interestingly, the activation of PI3K/AKT, MIF and CD74 are associated with chemoresistance, tumor progression, and metastasis via unknown mechanisms." (PMID 39056676, 2024). "Interestingly, both MIF and CD74 have been associated with tumor progression and metastasis." (PMID 39576827, 2024). "This study identified distinct tumor microenvironment states that align along an immunophenotype axis marked by CD74, interferon-γ, and APOBEC3 expression identified previously for primary CRC." (PMID 42298180, 2026). "CD74 has emerged as a complex prognostic biomarker across many cancer types, reflecting its dual role in both immune activation and tumor cell survival." (PMID 41597203, 2026). "Recent research has further elucidated the prognostic landscape of CD74 across multiple tumor types." (PMID 41597203, 2026).
tumor (continued). "The extent to which CD74 contributes to immune modulation in solid tumors appears to depend on both the cellular source (tumor vs. stromal) and the dominant signaling environment." (PMID 41597203, 2026). "Understanding how CD74 expression, processing, and signaling are altered in cancer is essential for deciphering its contribution to tumor progression and for optimizing strategies to therapeutically exploit this molecule." (PMID 41597203, 2026). "Given these diverse functions, CD74/Ii represents a critical intersection point between tumor cell biology, antigen presentation, and immune regulation." (PMID 41597203, 2026). "High CD74 expression predicts enhanced immunotherapy response in certain tumor types correlating with increased cytotoxic T cell infiltration and immune activation." (PMID 41597203, 2026). "We explore how tumor microenvironmental contexts redefine CD74 biology, influencing antitumor immunity and therapeutic outcomes." (PMID 41597203, 2026). "In some cancers, CD74 expression aligns with an inflamed tumor phenotype and higher immune infiltration, whereas in others it marks aggressive, immune-resistant disease." (PMID 41597203, 2026). "Collectively, these studies underscore the multifaceted prognostic value of CD74, reflecting both tumor-intrinsic oncogenic signaling and its role as a modulator of tumor–immune interactions." (PMID 41597203, 2026). "Overexpression of CD74, CLEC7A, and IFI30 in macrophages further enhanced M2 polarization, which was associated with increased tumor-promoting functions, including enhanced invasion and reduced apoptosis in GBM cells." (PMID 41892299, 2026). "MIF mediates its tumor-promoting effects through binding to CD74, thereby activating pathways such as PI3K/Akt, and stimulating angiogenesis via molecules such as VEGF and IL-8." (PMID 41597203, 2026). "In many types of cancer, overexpression of CD74 is accompanied by enhanced MIF-CD74 signaling, which drives tumor progression, metastasis, and poor clinical outcomes." (PMID 41597203, 2026). "Early studies showed that CD74 surface expression on malignant B cells not only marked tumor aggressiveness but also directly contributed to oncogenic signaling." (PMID 41597203, 2026). "Elevated expression of CD74 has been observed in a wide range of malignancies, highlighting its potential role in tumor biology beyond antigen presentation." (PMID 41597203, 2026). "Mechanistically, tumor cells can express distinct CD74 isoforms that differ in intracellular trafficking and MHC-II interactions." (PMID 41597203, 2026). "This dual functionality highlights the complex and context-dependent role of MHC-II+/CD74+ apCAFs in shaping tumor immunity, positioning them as both potential targets and modulators in immunotherapeutic strategies." (PMID 40940809, 2025). "For evaluating MSC migration into the tumors, MSC marker CD74- or sex determining region Y box 2 (SOX2)-positive cells in tumor tissues were detected by immunohistochemistry." (PMID 39940960, 2025). "Through transcriptomic sequencing analysis of tumours in WT and ApoE−/− mice, we observed that ApoE deficiency resulted in decreased expression levels of the immunologically relevant genes CCL24, CD74, and CX3CR1." (PMID 40662483, 2025). "Ongoing studies to evaluate CD74 expressing immune populations and their unique contribution in the tumor microenvironment will be informative, particularly in response to MIF‐pathway inhibition." (PMID 40131169, 2025). "It was found that tumor cells C2_STAT1+ and apCAF (Fib_CD74+) would induce the exhaustion of cytotoxic T cells (CD8T_CNLY+), leading to enhanced resistance to tumor treatment." (PMID 40948762, 2025). "The knockdown of CD74 or SUB1 suppresses tumor growth, and HGF has shown potential as a therapeutic target due to its role in fibrosis reversal and lung repair." (PMID 40136480, 2025).